KGD4 (alpha-ketoglutarate dehydrogenase subunit 4)
Description:
Molecular adapter that is necessary to form a stable 2-oxoglutarate dehydrogenase enzyme complex (OGDHC). Enables the specific recruitment of E3 subunit to E2 subunit in the 2-oxoglutarate dehydrogenase complex (OGDHC).
Synonyms: MRPS36; DC47; MRP-S36
Tractability: PROTAC: ubiquitination databases record sites on it.
Gene: Protein-coding gene on chromosome 5 (69,217,712 to 69,230,158, forward strand). Ensembl gene ENSG00000134056.
Subcellular location: Mitochondrion
Subcellular location (Human Protein Atlas): Mitochondria
Pathways (Reactome):
Metabolism of proteins: Mitochondrial ribosome-associated quality control; Mitochondrial translation elongation; Mitochondrial translation initiation; Mitochondrial translation termination
Metabolism: Glycine degradation; OGDH complex synthesizes succinyl-CoA from 2-OG
Gene Ontology:
Molecular function: protein-macromolecule adaptor activity
Biological process: 2-oxoglutarate metabolic process; tricarboxylic acid cycle
Cellular component: mitochondrion; mitochondrial inner membrane; oxoglutarate dehydrogenase complex
Genetic constraint (gnomAD): Loss-of-function variants: 7 observed, 9.27 expected, observed/expected ratio (o/e) 0.76, 90% interval 0.43 to 1.41. That is too few expected variants to judge how well the gene tolerates losing a copy. Missense variants: 86 observed, 95.42 expected, observed/expected ratio (o/e) 0.9, 90% interval 0.76 to 1.08. Synonymous variants: 21 observed, 31.54 expected, observed/expected ratio (o/e) 0.67, 90% interval 0.47 to 0.96.
Homologues: Orthologues: chimpanzee KGD4 (100% identical), dog MRPS36 (95% identical), rabbit KGD4 (91% identical), dog KGD4 (86% identical), pig KGD4 (85% identical), mouse Mrps36 (83% identical), guinea pig KGD4 (81% identical), rat Kgd4 (72% identical), rat AC132020.1 (71% identical), tropical clawed frog kgd4 (60% identical), zebrafish kgd4 (50% identical).
Diseases named in the same sentence as KGD4 in open-access papers:
KGD4 is named in the same sentence as 5 diseases in open-access papers, as found by Europe PMC text mining. Sharing a sentence is not in itself a finding about the gene and the disease.
KGD4 shares sentences with these, for which no sentence is quoted: developmental delay (1 paper); Dystonia (1); Leigh syndrome (1); Lupus (1); movement disorder (1).